COMMD3 (COMM domain containing 3)
Description:
Scaffold protein in the commander complex that is essential for endosomal recycling of transmembrane cargos; the commander complex is composed of the CCC subcomplex and the retriever subcomplex. May modulate activity of cullin-RING E3 ubiquitin ligase (CRL) complexes. May down-regulate activation of NF-kappa-B. Modulates Na(+) transport in epithelial cells by regulation of apical cell surface expression of amiloride-sensitive sodium channel (ENaC) subunits.
Synonyms: BUP; C10orf8
Tractability: Antibody: its Gene Ontology location is reachable by antibodies, with high confidence. PROTAC: ubiquitination databases record sites on it; its protein half-life has been measured.
Gene: Protein-coding gene on chromosome 10 (22,315,980 to 22,320,430, forward strand). Ensembl gene ENSG00000148444.
Subcellular location: Cytoplasm; Nucleus
Pathways (Reactome):
Immune System: Neutrophil degranulation
Metabolism of proteins: Neddylation
Gene Ontology:
Molecular function: protein binding
Biological process: endocytic recycling; sodium ion transport
Cellular component: cytoplasm; nucleus; protein-containing complex; endoplasmic reticulum membrane; endosome membrane; extracellular region; ficolin-1-rich granule lumen
Genetic constraint (gnomAD): Loss-of-function variants: 31 observed, 31.53 expected, observed/expected ratio (o/e) 0.98, 90% interval 0.74 to 1.33. The upper end of that interval is the gene's LOEUF score, 1.33, which puts it in group 5 of 6, group 1 being the genes least tolerant of losing a copy. Missense variants: 274 observed, 238.37 expected, observed/expected ratio (o/e) 1.15, 90% interval 1.04 to 1.27. Synonymous variants: 108 observed, 88.97 expected, observed/expected ratio (o/e) 1.21, 90% interval 1.04 to 1.42.
Homologues: Orthologues: chimpanzee COMMD3 (98% identical), guinea pig COMMD3 (94% identical), pig COMMD3 (93% identical), rabbit COMMD3 (91% identical), rat Commd3 (91% identical), mouse Commd3 (89% identical), tropical clawed frog commd3 (54% identical), zebrafish commd3 (51% identical), Drosophila melanogaster CG12106 (22% identical).
Diseases named in the same sentence as COMMD3 in open-access papers:
COMMD3 is named in the same sentence as 19 diseases in open-access papers, as found by Europe PMC text mining. Sharing a sentence is not in itself a finding about the gene and the disease. The quoted sentences say what the papers report.
hepatocellular carcinoma (5 papers, 2022 to 2025). A malignant tumor that arises from hepatocytes. "Although COMMD10 is known for its role in copper–iron homeostasis and radio-resistance in hepatocellular carcinoma, the functional role of COMMD3 in MM has remained unexplored." (PMID 40002764, 2025). "However, contrary to these observations, high levels of COMMD3 confer worse survival in hepatocellular carcinoma, indicating tissue-specific roles for COMMD3 in different cancers." (PMID 37072858, 2023). "By investigating the TCGA datasets, we found that the mRNA expression of COMMD3 was significantly upregulated in hepatocellular carcinoma tissue compared with normal liver tissue, which was further supported by Oncomine dataset, Western blot, qRT-PCR, and IHC analysis." (PMID 35399735, 2022). "High expression of copper metabolizing MURR1 domain (COMMD3) is significantly correlated with poor prognosis in hepatocellular carcinoma (HCC) patients." (PMID 36092163, 2022). "However, the role of COMMD3 in hepatocellular carcinoma are still unclear." (PMID 35399735, 2022).
prostate carcinoma (4 papers, 2021 to 2025). A carcinoma that arises from epithelial cells of the prostate gland. "This aligns with findings in prostate cancer, where COMMD3 promotes tumor growth by driving C-MYC transcription." (PMID 40002764, 2025). "Nevertheless, according to the literature, COMMD3 is expressed at a high level in prostate cancer, enhances migratory and invasiveness properties of tumor cells, and is also associated with tumor recurrence and low survival rate." (PMID 36092163, 2022). "High expression of COMMD3 was found in prostate cancer, and could promote tumor cell migration/invasiveness that associated with tumor recurrence and poor survival." (PMID 34493238, 2021). "COMMD3 activates oncogenes such as c-MYC, which promotes prostate cancer cell proliferation, migration, and invasion; COMMD3 expression is positively connected with tumor recurrence and decreased survival rate." (PMID 36776284, 2023).
breast carcinoma (2 papers, 2023). "Since ATP1B1 transcript has been reported to be upregulated in response to copper overload, this provides an initial hint that, similar to Commd1, Commd3 deficiency causes changes in copper homeostasis in breast cancer." (PMID 37072858, 2023). "Such transcriptional reprogramming could underpin the outgrowth of breast cancer cells with Commd3 loss." (PMID 37072858, 2023). "Overall, we found that COMMD3 loss promoted aggressive behaviour in breast cancer cells." (PMID 37072858, 2023). "Given the enrichment of shCOMMD3 cells in acini from our genetic screen and the robust expression of COMMD3 in well-differentiated, lower grade breast cancers, we next explored the tumour suppressor function of COMMD3 in more detail." (PMID 37072858, 2023). "Consistent with this, we observed an overload of copper in COMMD3 depleted cells along with an increase in copper levels in the highly metastatic 4T1.2 breast cancer cell line." (PMID 37072858, 2023). "Collectively, our data provided strong evidence that COMMD3 expression suppresses breast cancer growth in 3D culture and in vivo." (PMID 37072858, 2023). "We focused on COMMD3, a previously poorly characterised gene that suppressed invasive growth of ER + breast cancer cells in the cellular assay." (PMID 37072858, 2023). "Consistent with this, depletion of COMMD3 induced invasive spheroid growth in ER + breast cancer cell lines in vitro, while Commd3 depletion in the relatively indolent 4T07 TNBC mouse cell line promoted tumour expansion in syngeneic Balb/c hosts." (PMID 37072858, 2023). "For the first time, we report a novel role of COMMD3 as a negative regulator of tumour growth in breast cancer." (PMID 37072858, 2023). "This indicates that copper has a major role in breast cancer tumourigenesis and that COMMD3 acts to maintain copper homeostasis." (PMID 37072858, 2023). "We showed that COMMD3 is one of the many genes that can control tumour aggressiveness and provide evidence that copper chelation in COMMD3 low expressing cells would be a potential strategy to counteract disease progression and metastasis of breast cancer." (PMID 37072858, 2023). "In the TCGA breast cancer cohort, COMMD3 RNA was highest in luminal and HER2 + tumours, compared to basal- and normal-like subtypes." (PMID 37072858, 2023). "This indicated that COMMD3 is acting as a tumour suppressor in breast cancer." (PMID 37072858, 2023). "Moreover, subcellular fractionation of COMMD3 in T-47D, MDA-MB-231 and 4T07 breast cancer cell lines demonstrated that COMMD3 is higher in the cytoplasmic compared to nuclear fractions." (PMID 37072858, 2023). "The loss of COMMD3 promotes aggressive behavior in BRCA, suggesting the potential use of Cu chelation in COMMD3 low-expressing cells to improve disease progression and metastasis of breast cancer." (PMID 37535656, 2023). "Although COMMD3 depletion did not affect proliferation or cell cycle distribution of 4T07 tumours under standard 2D growth conditions, COMMD3 loss resulted in faster growing tumours, indicating that COMMD3 restrains breast cancer growth in vivo." (PMID 37072858, 2023). "In other words, for patients with luminal-A-like breast cancer who were still alive seven years after diagnosis, survival probability was lower for tumours lacking COMMD3 (e.g., 72.5% of patients alive at 10 years post-diagnosis, verus 83% for COMMD3 + cases (Fig-2H))." (PMID 37072858, 2023). "To study COMMD3 function in breast cancer, we utilised a non-metastatic 4T07-TGL (tagged with TK-GFP-luciferase) cell line that is syngeneic to Balb/c mice." (PMID 37072858, 2023). "Depletion of COMMD3 in non-aggressive breast cancer cells promoted an invasive phenotype." (PMID 37072858, 2023). "However, the expression and function of COMMD3 in human cancer, including breast cancer, is not well understood." (PMID 37072858, 2023).
breast carcinoma (continued). "Moreover, we found a negative association between high COMMD3 expression and tubule score, ELF5, c-Kit and AR expression in a large cohort of breast cancer cases." (PMID 37072858, 2023).
Multiple Myeloma (2 papers, 2025). "Through an integrated bioinformatics analysis and experimental validation, we demonstrated that COMMD3 plays a critical role in promoting multiple myeloma (MM) proliferation and metastasis, likely through EMT regulation and copper metabolism pathways." (PMID 40002764, 2025). "To explore the role of COMMD3 in multiple myeloma, we analyzed bulk RNA sequencing data (GSE6477), which demonstrated significant upregulation of COMMD3 in tumor samples compared to normal controls." (PMID 40002764, 2025). "Further research is necessary to delineate the role of ATOX1 in cancer cell migration, as the ATOX1-ATP7A-LOX axis and copper metabolism pathways were recently identified as COMM domain-containing protein 3 (COMMD3)-regulated signaling cascades involved in the progression of multiple myeloma." (PMID 40721800, 2025).
B-cell lymphoma (1 paper, 2023). "Notably COMMD3 is also reported to be lost in B-cell lymphoma." (PMID 37072858, 2023).
breast tumours (1 paper, 2023). "In particular, here, we demonstrated that COMMD3 loss is linked to aggressive breast tumour growth." (PMID 37072858, 2023). "We next investigated COMMD3 transcript levels in normal human breast and breast tumours by analysing published gene expression datasets." (PMID 37072858, 2023). "A modified COMMD3 IHC protocol was then applied to a consecutive series of invasive breast tumours sampled in tissue microarrays." (PMID 37072858, 2023).
metastatic prostate carcinoma (1 paper, 2023). A carcinoma that arises from the prostate gland and has spread to other anatomic sites. "The researchers discovered that COMMD3: BMI1 fusion expression was significantly elevated in metastatic prostate cancer." (PMID 36776284, 2023). "COMMD3: BMI1 fusion expression and COMMD3 protein increases significantly in metastatic prostate cancer; COMMD3 activates oncogenes such as c-MYC, promotes prostate proliferation, migration and invasion; Increased COMMD3 expression is positively correlated with tumor recurrence and reduced survival." (PMID 36776284, 2023).
monoclonal gammopathy of undetermined significance (1 paper, 2025). "Single-cell sequencing data from the monoclonal gammopathy of undetermined significance (MGUS) to MM samples also revealed a marked increase in COMMD3 expression, particularly in malignant plasma cells." (PMID 40002764, 2025).
prostate tumor (1 paper, 2020). "In addition, the hub gene Commd3 (COMM domain-containing 3) was shown to regulate c-myc transcription and prostate tumor growth in mice." (PMID 32831131, 2020).
thyroiditis (1 paper, 2020). Inflammation of the thyroid gland. "Under Bonferroni significance (P < 1.1 × 10−3), we identified rs56186224, a variant located in an enhancer linked to both COMMD3 and DNAJC1, to be associated with self-reported thyroiditis (P = 4.2 × 10−4)." (PMID 32371927, 2020). "Furthermore, we find an association between helper T cell content in thyroid tissue and a COMMD3/DNAJC1 regulatory variant (P = 7.5 × 10−10), which is associated with thyroiditis in other cohorts." (PMID 32371927, 2020).
tumor (8 papers, 2020 to 2025). "The high expression of COMMD3 is associated with adverse outcomes in a range of tumors and is related to the tumor’s abilities of migration, invasion, and angiogenesis." (PMID 40808953, 2025). "Lower tumour expression of COMMD3 mRNA was associated with a relatively lower probability of survival in the TCGA cohort." (PMID 37072858, 2023). "Analysis of published expression data suggested that COMMD3 is normally expressed in the mammary ducts and lobules, that expression is lost in some tumours and that loss is associated with lower survival probability." (PMID 37072858, 2023). "Expression of COMMD3 in luminal-A-like tumours was directly associated with markers of luminal differentiation: c-KIT, ELF5, androgen receptor and tubule formation (the extent of normal glandular architecture; p < 0.05)." (PMID 37072858, 2023). "COMMD3 had a strong correlation with markers of monocytes, tumor-associated macrophages (TAMs), M1 macrophages, neutrophils and Tregs in HCC." (PMID 34493238, 2021). "The expression of COMMD3 from GSE14520 dataset and 80 patients are both higher in tumor than that in normal tissue, and a higher level of COMMD3 mRNA is associated with shorter OS." (PMID 34493238, 2021). "In conclusion, this study suggests that COMMD3 may act as a novel regulator of MM proliferation and metastasis, with its potential tumor-promoting effects associated with the COMMD3/ATOX1-ATP7A-LOX axis and copper metabolism pathways." (PMID 40002764, 2025). "Interestingly, COMMD3 was significantly associated with markers of luminal differentiation and/or fate commitment in the luminal A-like tumours: tubule formation, androgen receptor (AR), ELF5 and cKIT (Fig-2I)." (PMID 37072858, 2023). "Interestingly, COMMD3 was inversely associated with the tubule score component of histological grade; that is, tumours that retain some of the polarization and alveolar-like structures typical of normal breast tissue were more likely to express higher levels of COMMD3 (ChiSq p = 3.0E−04)." (PMID 37072858, 2023). "This tumor-specific variability underscores the complexity of COMMD3’s function and highlights its dependence on cellular context and the tumor microenvironment." (PMID 40002764, 2025). "Using a xenograft tumor model, MM cells with COMMD3 overexpression displayed significantly accelerated tumor growth compared to the control, while COMMD3 knockdown led to a marked reduction in tumor size." (PMID 40002764, 2025). "DEGs identified in the COMMD3 knockdown group were enriched in pathways related to tumor metastasis, including cytokine production, angiogenesis, cell migration, and EMT." (PMID 40002764, 2025). "We performed immunohistochemical analysis of an independent tumour cohort to investigate relationships between COMMD3 protein expression, phenotypic markers and disease-specific survival." (PMID 37072858, 2023). "In null mice with subcutaneous xenograft tumors, silencing COMMD3 inhibited tumor development and expression of HIF1α, VEGF, and CD34." (PMID 36776284, 2023). "In order to further illustrate the function of COMMD3, we established xenograft tumor model using BALB/c nude mice." (PMID 35399735, 2022). "For this purpose, SK-Hep1 (as control), COMMD3-overexpressing cells, and COMMD3-knockdown cells were administrated into the nude mice subcutaneously to form a subcutaneous xenograft tumor model." (PMID 36092163, 2022). "Conversely, the COMMD3-knockdown group represented with decreased tumor growth rate and tumor weight (P < 0.001)." (PMID 36092163, 2022). "The tumor growth rate and tumor weight in mice administered with the COMMD3-overexpressing cells showed a significant increase compared to the control group (P < 0.001)." (PMID 36092163, 2022). "Then, we showed that COMMD3 was more highly expressed in tumor tissues than in normal tissues from GSE14520 and 80 patients, was associated with poor OS and was an independent prognostic factor for shorter OS." (PMID 34493238, 2021).
tumor (continued). "COMMD3 expression was higher in tumor tissues than normal tissues in GSE14520 dataset between one thirds of the highest expression and two thirds of the lowest expression (p < 0.001)." (PMID 34493238, 2021). "Additionally, a tail vein injection model also demonstrated that COMMD3 overexpression significantly increased both tumor formation and metastasis, reinforcing its role in MM progression and metastasis." (PMID 40002764, 2025). "Conversely, downregulation of COMMD3 effectively inhibited this tumor-promoting process." (PMID 40808953, 2025). "Finally, we established xenograft tumor model in nude mice, and the knockdown of COMMD3 suppressed tumor growth and angiogenesis." (PMID 35399735, 2022). "Finally, the xenograft tumour assay using nude mice showed that COMMD3 knockdown inhibited tumor growth and the expression of HIF1α, VEGF and CD34." (PMID 35399735, 2022). "QT-PCR results showed that the subtracts mean CT of COMMD3 and Actin were higher in normal tissue than tumor tissue using paired t-test, which mean COMMD3 were more highly expressed in tumor tissues than in paired normal tissues from 80 HCC patients (p < 0.05)." (PMID 34493238, 2021). "The results from human HCC cells lines supported that lower expression of COMMD3 may influence tumor development via suppressing cell proliferation." (PMID 34493238, 2021). "One reason for this is COMMD3 could stimulate interferon expression to influence immunity, while macrophages can strengthen their killing effect on tumor cells by acting interferon." (PMID 34493238, 2021). "However, the relationship between COMMD3 and tumor angiogenesis has rarely been studied." (PMID 36092163, 2022). "In the subnetwork related to tumor progression, the hubs from the blue module are the most connected, such as the genes Cmas, Kmt2a, Golt1b, Cdc34, Manf, Sco1, and Thoc3, followed by hubs from the light cyan (Extl2, Commd3, Wdr41, Keap1, Osbpl9) and pink modules." (PMID 32831131, 2020). "Consistent with the transcript analyses, COMMD3 protein levels were significantly higher in ER + and HER2 + tumours compared to TNBC." (PMID 37072858, 2023). "The outcomes of IHC staining also illustrated that the tumor staining intensity of β-Catenin and CD34 in the COMMD3-overexpressed group was higher than that of the control group, while the COMMD3-RNA interference group had lower intensity." (PMID 36092163, 2022). "The IHC and western blotting results showed that expression levels of COMMD3, HIF1α, VEGF and CD34 proteins in xenograft tumours from LV-Con group were significantly higher than those from LV-ShCOMMD3 group." (PMID 35399735, 2022). "Notably, pathways involved in tumor metastasis, such as epithelial–mesenchymal transition (EMT), were significantly enriched, suggesting a potential link between COMMD3 expression and metastatic progression." (PMID 40002764, 2025). "We identified known tumour suppressors, including CEBPA and novel candidates such as COMMD3." (PMID 37072858, 2023). "This revealed an association between COMMD3 loss and shorter survival in hormone-dependent breast cancers and in particularly luminal-A-like tumours (ER+/Ki67-low; 10-year survival probability 0.83 vs. 0.73 for COMMD3-positive and -negative cases, respectively)." (PMID 37072858, 2023).
cancer (3 papers, 2022 to 2025). A tumor composed of atypical neoplastic, often pleomorphic cells that invade other tissues. "We provide evidence that COMMD3 controls copper levels in cancer cells." (PMID 37072858, 2023). "Both in vitro and in vivo results verified cancer- and angiogenesis-promoting effects of COMMD3." (PMID 36092163, 2022).
infection (1 paper, 2022). The state of being infected such as from the introduction of a foreign agent such as serum, vaccine, antigenic substance or organism. "Many of the hits were associated with intracellular transport or endosome activity, including VPS29, the CCDC22/CCDC93/COMMD3 (CCC) complex, and the WDR81/91 complex, suggesting a requirement for these functions in HCoV-OC43 infection." (PMID 35229640, 2022).
COMMD3 also shares sentences with these, for which no sentence is quoted: Anxiety (1 paper); attention deficit-hyperactivity disorder (1); hypothyroidism (1); Insulin resistance (1); liver cancer (1); ovarian carcinoma (1).